APOE (apolipoprotein E)
Diseases named in the same sentence as APOE in open-access papers (continued):
Sharing a sentence is not in itself a finding about the gene and the disease.
Alzheimer disease (continued). "Although the APOE region is the strongest genetic risk factor for Alzheimer's diseases (ADs), its pathogenic role remains poorly understood." (PMID 29797398, 2018). "Is interaction of chronic low-grade inflammation and the apolipoprotein E genotype associated with development of Alzheimer disease?" (PMID 30646251, 2018). "Genetic variation at two SNPs (rs429358 and rs7412) in the APOE gene result in three alleles, of which the ε4 allele is well established to increase the risk of developing Alzheimer’s disease in a dose-dependent manner." (PMID 30097731, 2018). "The APOE ε4 allele is a strong genetic risk factor for Alzheimer’s disease, whereas the APOE ε2 allele is protective." (PMID 30348994, 2018). "Multifactorially adjusted hazard ratios for Alzheimer’s disease and all dementia were 2.72 (2.45–3.01) and 2.21 (2.05–2.38) per APOE rs425358 C allele (ɛ4 allele)." (PMID 29534716, 2018). "Our study identified 21 participants with one or two copies of the APOE e4 allele, which significantly increases lifetime risk for developing Alzheimer's disease." (PMID 30487145, 2018). "APOE regulates cholesterol metabolism and is believed to modulate the clearance of amyloid-beta, the accumulation of which is a hallmark of Alzheimer’s disease." (PMID 30339707, 2018). "This population-based cohort study uses data from the Framingham Heart Study offspring cohort to study the interaction between the apolipoprotein E genotype and chronic low-grade inflammation and its association with the incidence of Alzheimer disease." (PMID 30646251, 2018). "Among these genes, apolipoprotein E (ApoE) is particularly compelling because the human ApoE isoform E4 is a risk factor for the development of Alzheimer’s disease, where hippocampal neurogenesis is reported to be dysfunctional." (PMID 30079373, 2018). "Next, we assessed the ancestral background of ApoE alleles (“local” ancestry) and tested if ancestry local to ApoE influenced Alzheimer disease risk while controlling for global ancestry." (PMID 30517106, 2018). "We examined metabolic brain networks of young adults, patients with Alzheimer's disease, and four subgroups of cognitively normal older adults based on the presence or absence of two Alzheimer's risk factors: Aβ deposition and the ApoE ε4 allele." (PMID 29527500, 2018). "Three common polymorphisms of the APOE gene exist (E2, E3 and E4) and multiple copies of the APOE4 increases disease risk significantly and are associated with an earlier age of onset of Alzheimer’s disease." (PMID 30509933, 2018). "While excluding the APOE/TOMM40 region (containing the single largest genetic risk factor for late-onset Alzheimer's dementia) in the calculation of the PRS resulted in a slightly weaker association with the molecular signatures, results remained significant." (PMID 30349450, 2018). "The apolipoprotein-E (APOE) epsilon 4v variant is a risk gene variant for Alzheimer’s disease, which has been investigated for brain blood flow in relation to memory testing in age- and sex-matched participants from OBB." (PMID 29040543, 2018). "The APOE ε4 allele is a well-established risk factor for Alzheimer’s disease (AD) which also negatively impacts healthy cognitive aging." (PMID 29856823, 2018). "Alzheimer’s disease (AD) is a genetically complex process where ε4 allele of the APOE gene (APOE4) is by far the best-established genetic susceptibility risk factor." (PMID 30208929, 2018). "Previous research suggests a connection between sleep deprivation and pathological signs of Alzheimer’s disease (AD), a dementia subtype for which old age and presence of the apolipoprotein E (APOE) ε4 allele are among the strongest risk factors." (PMID 30076495, 2018). "The apolipoprotein E (APOE) ε4 allele is a major genetic risk factor for late-onset Alzheimer's disease (AD) which affects nearly 5 million individuals over the age of 65." (PMID 28333036, 2017).
Alzheimer disease (continued). "The three ApoE variants have been reported to differentially impact the development and progression of late-onset Alzheimer’s disease (LOAD)." (PMID 28934977, 2017). "We have shown that this DNA motif is repeated several times within exon 4 of apolipoprotein E, which harbors these Alzheimer’s disease alleles." (PMID 28094792, 2017). "An elevated level of apoE is also a risk factor for Alzheimer’s disease and possibly can be involved in PD." (PMID 28695482, 2017). "The APOE E4 allele has been associated with Alzheimer’s disease, higher levels of low density cholesterol (LDL-C) and a greater risk of coronary heart disease compared to E3 (wild-type) and E2 carriers." (PMID 29143670, 2017). "The ε4 allele of apolipoprotein E (ApoE) has been identified as an important susceptibility gene for Late Onset Alzheimer Disease (LOAD), while many other genes also associated with LOAD susceptibility to varying degrees." (PMID 29069820, 2017). "Altered structure and function of ApoE protein is associated with neurodegenerative disorders such as Alzheimer's disease (AD)." (PMID 28487499, 2017). "Brain APOE has been strongly implicated in mechanisms associated with neurodegenerative diseases including Alzheimer’s disease." (PMID 29770778, 2017). "The most significant genetic risk factor for late onset Alzheimer’s disease is a variant of the apolipoprotein E gene, APOE4." (PMID 28094792, 2017). "There are three different versions of apoE that are associated with different levels of risk of developing Alzheimer’s disease." (PMID 28994390, 2017). "The APOE-ε4 risk allele is also consistently linked to cognitive decline, particularly in the context of pathological dementia and Alzheimer's disease." (PMID 28983317, 2017). "The apolipoprotein ε4 gene allele and the apolipoprotein E4 protein (ApoE4) are important host susceptibility factors linked to neurocognitive disorders associated with HIV infection or Alzheimer’s disease." (PMID 28321820, 2017). "The APOE ε4 allele is known to increase the risk of late-onset Alzheimer disease (AD) as well as of cardiovascular diseases." (PMID 28873088, 2017). "On the other hand, the APOE2 allele of APOE is protective against Alzheimer’s Disease, with an OR = 0.6 for APOE2/APOE2 individuals." (PMID 28094792, 2017). "Participant 15 was informed he had an LP variant associated with Brugada syndrome and was one of two participants who received APOE e4/e4 results indicating increased Alzheimer's disease risk." (PMID 28051073, 2017). "In this meta-analysis, we were able to identify 23 eligible publications on APOE gene polymorphisms and risk of Alzheimer's disease (AD) that satisfied the inclusion criteria of the study." (PMID 28900374, 2017). "It is notable that one participant's focus shifted over several months from his Brugada-associated rare variant result to his Alzheimer's disease APOE e4/e4 result, as he processed and dealt with each in turn." (PMID 28051073, 2017). "The APOE locus presents a prime example of the pleiotropic influence of genes on both cognitive function and lifespan and has been consistently implicated in Alzheimer's disease and human longevity." (PMID 28983317, 2017). "While age and the APOE ε4 allele are major risk factors for Alzheimer’s disease (AD), a small percentage of individuals with these risk factors exhibit AD resilience by living well beyond 75 years of age without any clinical symptoms of cognitive decline." (PMID 29183403, 2017). "Many studies have shown that healthy elderly subjects and patients with Alzheimer’s disease (AD) who carry the apolipoprotein E (ApoE) ε4 allele have worse cognitive function and more severe brain atrophy than non-carriers." (PMID 28706481, 2017). "The APOE ε4 allele is the most significant common genetic risk factor for late-onset Alzheimer’s disease (LOAD)." (PMID 28589856, 2017).
Alzheimer disease (continued). "Inheritance of the apolipoprotein E4 (apoE4) genotype has been identified as the major genetic risk factor for late onset Alzheimer’s disease (AD)." (PMID 28808293, 2017). "In our sample, the APOE ε4 allele (Alzheimer disease risk allele) frequency was higher in those who adhered more to the MeDi." (PMID 28053008, 2017). "Several studies have evaluated the role of polymorphisms in the promoter region of APOE gene that encodes apolipoprotein E (APOE) and the susceptibility to Alzheimer's disease (AD)." (PMID 28900374, 2017). "The association of ApoE genetic polymorphism with Alzheimer's disease (AD) has also been addressed in epidemiological studies and experimental animal studies." (PMID 28824412, 2017). "APOE polymorphism has been associated with the risk of developing many central nervous system disorders, like Alzheimer’s disease, vascular dementia, multiple sclerosis, cerebral infraction and Parkinson’s disease." (PMID 29213291, 2017). "A previous study demonstrated lower CSF Aβ-42 levels in carriers of the ε4 allele of the apolipoprotein E (APOE) gene, but recent data show that this is mediated via the association of ε4 with senile plaque pathology in Alzheimer’s disease." (PMID 28039552, 2017). "Apolipoprotein E (APOE) ε4 is by far the most replicated risk allele for late onset Alzheimer’s disease (AD)." (PMID 28672022, 2017). "Triggering receptor expressed on myeloid cells 2 (TREM2) and apolipoprotein E (APOE) are genetically linked to Alzheimer’s disease." (PMID 28320424, 2017). "In the three-factor model, rs429358 is one of two main SNPs in the Apolipoprotein E (APOE) gene associated with late-onset Alzheimer’s disease (LOAD), with the C allele being pathogenic." (PMID 28572842, 2017). "The APOE ε4 allele has been recognized as the strongest genetic risk factor for late-onset Alzheimer's disease (LOAD) in several populations worldwide, yet the risk varies by region and ethnicity." (PMID 29348964, 2017). "Numerous epidemiological studies suggest a key role of peripherally expressed APOE in the development and progression of coronary heart disease while brain APOE has been associated with dementia and Alzheimer’s disease." (PMID 29770778, 2017). "The apolipoprotein-ε4 allele (APOE-ε4) is strongly associated with detrimental outcomes in affluent populations including atherosclerotic disease, Alzheimer’s disease, and reduced lifespan." (PMID 28683096, 2017). "The risk that an individual with APOE-e4/e4 will develop Alzheimer disease dementia has been reported to be as high as 50%–67%, but these estimates come from statistical modeling, not direct observation." (PMID 28323826, 2017). "Apolipoprotein E genetic polymorphism and ApoEe4 alleles are known to be associated with Alzheimer's disease." (PMID 29326545, 2017). "The apolipoprotein E4 (ApoE4) genotype combines with traumatic brain injury (TBI) to increase the risk of developing Alzheimer’s Disease (AD)." (PMID 28900205, 2017). "Possession of the ε4 allele of apolipoprotein E (APOE) is the major genetic risk factor for late-onset Alzheimer's disease (AD)." (PMID 29311783, 2017). "More than two decades after the first report describing a significantly increased risk of developing late-onset Alzheimer’s disease (AD) in carriers of the APOE ε4 allele, this allele remains the strongest genetic risk factor for AD." (PMID 28137305, 2017). "In Alzheimer’s disease (AD) patients, apopoliprotein (APOE) polymorphism is the main genetic factor associated with more aggressive clinical course." (PMID 29062035, 2017). "We first identified 500 relevant publications on APOE gene polymorphisms and the risk of Alzheimer's disease (AD)." (PMID 28900374, 2017). "Alzheimer's disease (AD) is the most common form of dementia in the elderly; important risk factors are old age and inheritance of the apolipoprotein E4 (APOE4) allele." (PMID 28634550, 2017).
Alzheimer disease (continued). "Apolipoprotein E4 (ApoE4) is a major genetic risk factor for sporadic or late onset Alzheimer’s disease (AD)." (PMID 28569173, 2017). "The apolipoprotein E ε4 allele (APOE*4) is an established risk factor for Alzheimer disease (AD) and for the transition from MCI to AD." (PMID 28323832, 2017). "The ε4 allele of apolipoprotein E (APOE) is the dominant genetic risk factor for late-onset Alzheimer’s disease (AD)." (PMID 29133888, 2017). "Carriers of the APOE ε4 allele are at increased risk of developing Alzheimer’s disease (AD), and have been shown to have reduced cerebral metabolic rate of glucose (CMRgl) in the same brain areas frequently affected in AD." (PMID 28137305, 2017). "Apolipoprotein E (ApoE) ε4 allele has been proved to be a risk gene of late-onset Alzheimer's Disease (AD)." (PMID 28396874, 2017). "The apolipoprotein E ɛ4 (APOE4) allele is the strongest genetic risk factor identified for developing Alzheimer’s disease (AD)." (PMID 28335828, 2017). "The presence of the APOE 4 allele has also been related to amyloid beta accumulation in the brain, which is of great importance in the pathogenesis of Alzheimer’s disease." (PMID 27240396, 2016). "In the REVEAL trial, the investigators reported that in those individuals with a family history of Alzheimer’s disease (AD), knowledge of an APOE ɛ4+ risk genotype was positively associated with dietary supplement use." (PMID 27708721, 2016). "Among ApoE-ε4 carriers, individuals with the GG + GA genotype showed a significantly increased risk of Alzheimer's disease (OR = 3.46, 95% CI: 1.78–6.71, P < 0.001)." (PMID 27597977, 2016). "Most importantly, genome-wide association studies have confirmed that the ε4 allele of APOE is the strongest genetic risk factor for late-onset Alzheimer’s disease (LOAD)." (PMID 26754117, 2016). "The apolipoprotein E (APOE) gene is the most highly associated susceptibility locus for late onset Alzheimer’s Disease (AD), and augmenting the beneficial physiological functions of apoE is a proposed therapeutic strategy." (PMID 27598782, 2016). "Over the past two decades, the APOE gene and its polymorphisms have been among the most studied risk factors of Alzheimer disease (AD) development; yet, there are discrepancies between various studies regarding their impact." (PMID 27193889, 2016). "Further, we provide a conceptual framework that suggests an interaction between mitochondrial haplotypes and two demonstrated risk factors for Alzheimer’s disease (AD), apolipoprotein E (APOE) genotype and chromosomal sex." (PMID 27757081, 2016). "We assessed the extent of the association of APOE genotype, the main genetic risk factor for sporadic Alzheimer’s disease, and altered microglial expression." (PMID 27256292, 2016). "Alzheimer’s disease risk increases significantly in individuals carrying one or two copies of APOE ε4 allele compared to individuals with an ε3/ε3 genotype." (PMID 27151330, 2016). "The apolipoprotein (APOE) gene, encoding APOE involved in lipid metabolism, is a well-established risk factor for Alzheimer’s disease (AD)." (PMID 27757080, 2016). "Including the well documented association with the gene APOE, previous studies have identified 22 susceptibility loci for late-onset Alzheimer’s disease (LOAD), of which 11 were recently reported by a large meta-analysis." (PMID 26788126, 2016). "The apolipoprotein E (APOE) gene is well-known for its association with Alzheimer’s disease, but has also been related to other disorders of importance for aging." (PMID 27757080, 2016). "Higher V ̄P‐reactivity in APOE ε4 carriers suggests vascular compensation for deleterious effects of this known risk allele for Alzheimer's disease and stroke." (PMID 27117804, 2016). "The genetic studies also re-emphasized apolipoprotein E (APOE) genotype as the main risk factor for sporadic Alzheimer’s disease." (PMID 27256292, 2016).
Alzheimer disease (continued). "More importantly, TOMM40 rs10524523 polymorphism in combination with APOE alleles significantly influences late-onset Alzheimer’s disease and longevity." (PMID 27060904, 2016). "Apolipoprotein E4 (ApoE4), one of three common isoforms of ApoE, is a major risk factor for late-onset Alzheimer disease (AD)." (PMID 27171180, 2016). "The APOE gene and its polymorphic variants investigated here are described in the literature primarily as genes predisposed to Alzheimer’s disease." (PMID 27240396, 2016). "Apolipoprotein E4 (apoE4), the leading genetic risk factor for Alzheimer's disease (AD), is less lipidated compared to the most common and AD-benign allele, apoE3." (PMID 27824936, 2016). "The apolipoprotein E (APOE) ε4 allele associates with accelerating the conversion from amnestic mild cognitive impairment (aMCI) to Alzheimer's disease (AD), whereas the protectiveAPOEε2 allele appears to be against the disease." (PMID 27542235, 2016). "Apolipoprotein (APOE) ɛ4 genotype has been identified as a risk factor for late-onset Alzheimer disease (AD)." (PMID 27395443, 2016). "Based on this result, we suggest that APOE genotyping can be added to the items of newborn screening programs to detect infants with a high risk of Alzheimer’s disease, cardiovascular diseases, and type 2 diabetes." (PMID 27078154, 2016). "An intriguing gate-keeper of this mitochondrial import process is TOMM40, the gene for which is located within the APOE block of linkage disequilibrium that confers susceptibility to Alzheimer's Disease, as discussed later." (PMID 27242399, 2016). "Under the existence of ApoE-ε4, the risk of Alzheimer's disease increased notably when the genotype of rs3810950 was GG + GA or AA." (PMID 27597977, 2016). "A related source of evidence comes from comparing healthy carriers of the apolipoprotein (APOE) ε4 allele, which increases the risk of Alzheimer’s disease, withAPOEε2 allele carriers, which protect against Alzheimer’s disease (Corderet al., 1993)." (PMID 27190025, 2016). "Risk factors for Alzheimer’s disease include genetic risk factors, such as possession of ε4 allele of apolipoprotein E (ApoE4) over the risk-neutral ApoE3 allele, and lifestyle risk factors, such as diet and exercise." (PMID 26828652, 2016). "ApoE exists as three major isoforms, termed apoE2, apoE3 and apoE4, of which apoE4 is the most prevalent genetic risk factor for Alzheimer's disease (AD)." (PMID 27824936, 2016). "Here we used the triple network model to investigate the large-scale brain networks in cognitively normal apolipoprotein e4 (APOE4) carriers who are at risk of Alzheimer’s disease (AD)." (PMID 27733827, 2016). "In this study, we analyzed individuals who are APOE ε4 risk allele carriers but are resilient to Alzheimer’s disease, and discovered a novel AD protective genetic variants modifying AD risk in APOE ε4 risk allele carriers." (PMID 27358062, 2016). "APOE ε4 is the strongest genetic risk factor for late-onset Alzheimer’s disease (AD) and accounts for 50–65% of late-onset AD." (PMID 27462267, 2016). "The apolipoprotein E (APOE) e4 genotype is a powerful risk factor for late-onset Alzheimer’s disease (AD)." (PMID 27065111, 2016). "Given its role in cognition and its association with the Alzheimer's disease (AD) risk gene, apoE, ApoER2 has been proposed to be involved in AD, though a role for the receptor in the disease is not clear." (PMID 26902204, 2016). "Presence of the apolipoprotein E ε4 (APOE ε4) allele is associated with increased risk of Alzheimer’s disease (AD)." (PMID 27441602, 2016). "The strongest overall signal in the meta-analysis was between diagnostic status for Alzheimer’s disease and a group of SNPs in the region of the APOE gene." (PMID 26625115, 2015). "The apolipoprotein E (APOE) genotype is the strongest genetic risk factor for Alzheimer’s disease (AD)." (PMID 26397226, 2015).